RUNX1 (RUNX family transcription factor 1)
Diseases named in the same sentence as RUNX1 in open-access papers (continued):
Sharing a sentence is not in itself a finding about the gene and the disease.
thymic lymphoma (1 paper, 2017). "In thymic lymphoma cells Runx1 expression consistently regulates sphingolipid metabolism to favor S1P production with concomitant reduction in long chain ceramides." (PMID 27869314, 2017). "Together the data support a mechanism whereby the opposition of Sgpp1 transcription and the overexpression of Ugcg might contribute to Runx1‐induced survival in the presence of dexamethasone in thymic lymphoma cell lines." (PMID 27869314, 2017).
tropical spastic paraparesis (1 paper, 2025). "Impaired silencer function from RUNX1 mutations could lead to aberrant viral protein expression and influence clinical outcomes, such as early ATL or HAM and tropical spastic paraparesis." (PMID 40360701, 2025).
tuberculosis (1 paper, 2018). A chronic, recurrent infection caused by the bacterium Mycobacterium tuberculosis. "Notably, the levels of CD82 and RUNX1 in granulomas were elevated in tuberculosis (TB) patients, indicating that CD82 and RUNX1 have clinical significance in human TB." (PMID 29760437, 2018).
Tuberous sclerosis complex (1 paper, 2022). "Tuberous sclerosis complex is characterized by a mutation in TSC1 or TSC2 which activates the signal pathway of mTORC1/RUNX1/EGFR with loss of function." (PMID 36231025, 2022).
uveitis (1 paper, 2023). An inflammatory process affecting a part of or the entire uvea. "Targeted genes of miR-146a were thus up-regulated and enriched in previews mentioned underline pathogenesis of uveitis such as interferon α/β, interferon γ, Rho GTPases, Miro GTPases, and RHOBTB3, metalloprotease class of deubiquitinases, RUNX1." (PMID 36969183, 2023).
vascular dementia (1 paper, 2025). A degenerative vascular disorder affecting the brain. "The presence of CLDN5 in tight junction expression under RunX1 underlines its role in blood-brain barrier integrity, a key factor in vascular dementia." (PMID 41032496, 2025).
ventricular dilation (1 paper, 2024). "Runx1 OE from birth results in left ventricular dilation, thinning of the posterior wall, and decreased ejection fraction, with varying influence from the injury itself." (PMID 38847758, 2024).
viral hepatitis (1 paper, 2021). An acute or chronic inflammation of the liver parenchyma caused by viruses. "As for viral hepatitis, exosomal miRNAs have been shown to regulate multiple signaling pathways, whereas few exosomal lncRNAs (RUNXOR and RUNX1) have been demonstrated to be involved in the development of viral hepatitis." (PMID 34753929, 2021).
tumor (383 papers, 2004 to 2026). "Analysis of clinical CRC tissues revealed that RUNX1 expression is negatively correlated with GITRL levels in tumor cells and is associated with increased infiltration of Treg cells." (PMID 41881966, 2026). "This difference reflects distinct selective pressures, where recurrent mutations in tumor suppressors favorably exhibit complete LoF mechanisms, as demonstrated experimentally for RUNX1." (PMID 41497600, 2025). "In the cell clusters collected from the lung (C2, C3, C12, C13, and C19), shared TFs among malignant and precancerous cells included LTF, IRX5, SIX1, and RUNX1, associated with tumor invasion and metastasis." (PMID 39872221, 2025). "Subsequently, the subcutaneous tumor formation in nude mice also confirmed that BMP2 can reverse the growth inhibition caused by RUNX1 knockdown, and also reverse the reduction in vasculogenic mimicry density." (PMID 38610001, 2024). "The qPCR analysis (n = 66) revealed an elevated expression of RUNX1 in tumor tissues (P < 0.0001), and the positive associations between RUNX1 mRNA and CD163 mRNA, Arg1 mRNA, CD68 mRNA, CD206 mRNA, IL-10 mRNA were observed (all P < 0.05)." (PMID 38419056, 2024). "Adding further information to this context, a recent publication by Kodgule and colleagues showed that ERG binds to GGAA microsatellite enhancers and activates according genes in ETV6-deficient or ETV6::RUNX1-positive tumor cells." (PMID 39202339, 2024). "Our findings indicated a notable increase in RUNX1 levels in cancerous tissues, associated with more aggressive tumor characteristics and a poorer prognosis." (PMID 39309442, 2024). "Here, by dissecting the transcriptome dynamics of tumor‐associated macrophage at single‐cell resolution, a crucial role of a hematopoietic transcription factor Runx1 in MMT formation is revealed." (PMID 37967345, 2024). "RUNX1 downregulation led to decreased tumor volumes and weights, confirming that RUNX1 deficiency impeded tumor growth in vivo." (PMID 39309442, 2024). "We aimed to investigate the RUNX1 mediated crosstalk between tumor cells and M2 polarized tumor associated macrophages (TAMs) in CRC, as well as its relationship with neoplastic angiogenesis." (PMID 38419056, 2024). "In the first place, most of the characterized RUNX1 mutations/translocations result in loss of function, suggesting that wild-type RUNX1 plays a tumor-suppressive role." (PMID 37670378, 2023). "A tumor-suppressor role for RUNX1 was proposed based on observed loss of function mutations to RUNX1 in T-ALL." (PMID 37213235, 2023). "Further, RUNX1 loss impairs tumor initiation and maintenance and the growth of oral, skin, and ovarian epithelial human cancer cells through inhibition of the JAK/STAT pathway." (PMID 36831211, 2023). "Aberrations of tumour suppressor genes were evenly distribution between RUNX1-mutated and wt-cohorts (16 vs. 12%)." (PMID 37188777, 2023). "Given that the majority of RUNX1 mutations detected in these patients are defined as loss-of-function mutations, RUNX1 is considered to function primarily as a tumor suppressor in these cancers." (PMID 36429115, 2022). "RUNX1 was reported to be associated with proliferation, inhibition of apoptosis, and tumor metastasis and invasion." (PMID 36339002, 2022). "The RUNX1 transcription factor is considered to be a regulator which, by mutation, can cause tumor-related epigenetic aberrations." (PMID 36005134, 2022).
tumor (continued). "Existing clinical studies have shown that tumour cells rely more than normal cells on a high level of SE-driven transcriptional regulation mediated by specific oncogenes, such as RUNX1 (encoding RUNX family transcription factor 1) in AML and MYCN in NB." (PMID 35303940, 2022). "By analysing transcription factors (TFs) with evidence of BTLA promoter binding in ChIPseq, we found each variant tumour possessed a mutation predicted to disrupt TF binding, most frequently RUNX1/3, GATA3 and MYB." (PMID 34753926, 2021). "Our data indicate that miR-30d is a key tumor-suppressive molecule for regulation of the Warburg effect and also indicate a causal role for miR-30d/RUNX1 axis in glycolysis regulation." (PMID 34021267, 2021). "Over-expression of RUNX1 caused increasing cell proliferation and invasion, suggesting that RUNX1 contributed to the tumor growth by modulating miR-582-5p expression." (PMID 33937021, 2021). "We next assessed the association between RUNX1, glycolysis components, and overall survival after tumor resection in the PDAC TMA and another 2 cohorts." (PMID 34021267, 2021). "A prior study also revealed shown that RUNX1 can inhibit Yes-associated protein (YAP) to accelerate the occurrence of tumor." (PMID 33061847, 2020). "Nuclear FAK is specifically linked to IGFBP3 through its interaction with Runx1, which leads to cell cycle progression and tumor growth regulation." (PMID 33240810, 2020). "Loss of Nf1 activates RUNX1/3 to enable tumor initiation by repressing Pmp22 through alternative promoter usage and other mechanisms to induce protein level expression of PMP22." (PMID 31032403, 2019). "To identify the genes that are directly regulated by Runx, we performed chromatin immunoprecipitation sequencing (ChIP-seq) to assess the genome-wide occupancy of RUNX1 in Nf1-deficient tumor cells." (PMID 31032403, 2019). "RUNX1 has been implicated as a tumor suppressor in solid tumors, including breast cancer, esophageal adenocarcinoma, colon cancer, and possibly, prostate cancer and as an oncogene in skin cancer, endometrial cancer, and epithelial cancer." (PMID 31032403, 2019). "Our study supports this finding as, in two of the six studied patients, the RUNX1 gene is affected by mutations in all tumor steps and the patients experienced progression of the disease in spite of treatment with the aromatase inhibitor Letrozole." (PMID 29293529, 2018). "In human cancer cells, Runx1 loss impairs tumor initiation and maintenance and the growth of oral, skin, and ovarian epithelial human cancer cells." (PMID 30046048, 2018). "Strikingly, significant reductions in Ebf1, Tcf3 (encoding E2A), and Runx1 transcripts were observed in tumor compared to unaffected EB cells." (PMID 28692033, 2017). "Runt-related transcription factor 1 (RUNX1) is a key hematopoietic transcription factor that regulates genes involved in myeloid differentiation, and is generally considered to be a classical tumor suppressor (class II) mutation." (PMID 28933735, 2017). "As tumor metastasis is the main cause of morbidity and mortality, we explored the ability of Runx1 to promote tumor aggressiveness." (PMID 26735887, 2016). "More extensive evidence of a tumor suppressor role for RUNX1 has come from myeloid malignancies where loss of function mutation is frequently observed in AML, and underlies familial platelet disorder with predisposition to AML." (PMID 27056890, 2016). "The capability of E2 and G-1 in triggering the induction of miR144 and the down-regulation of Runx1 was also confirmed in cancer-associated fibroblasts (CAFs) that are main components of the tumor microenvironment driving cancer progression." (PMID 26030000, 2015).
tumor (continued). "In a univariate analysis the presence of RUNX1 was associated with poorer cancer-specific survival for patients with ER- tumours (p<0.05) and showed a tendency towards significance as an independent prognostic marker in multivariate analysis (p = 0.058)." (PMID 24967588, 2014). "In contrast, in those patients with triple negative receptor status only the tumour CD4 lymphocytic infiltrate was significantly associated with positive RUNX1 protein levels (P<0.05)." (PMID 24967588, 2014). "RUNX1 was associated with progesterone receptor (PR)-positive tumours (P<0.05), more tumour CD4+(P<0.05) and CD8+(P<0.01) T-lymphocytic infiltrate, increased tumour CD138+plasma cell (P<0.01) and more CD68+macrophage infiltrate (P<0.001)." (PMID 24967588, 2014). "In the whole cohort a number of factors were identified to be associated with positive RUNX1 protein levels including age (P<0.05), ER status (P<0.10), PR status (P<0.05), tumour lymphocyte and macrophage infiltrate (all P<0.05)." (PMID 24967588, 2014). "In the light of data revealing a tumour-suppressor role for caspase-2, we were intrigued by the identification of the cancer-associated proteins Runx1 and 3 as potential caspase-2 substrates." (PMID 27919034, 2014). "Given that caspase-2 has been shown to reside in the nucleus and possess a tumour-suppressor function, the cancer-associated transcription factor Runx1 was an attractive candidate substrate for this protease." (PMID 27919034, 2014). "According to previous studies, the overexpression of the fusion protein, Runx1-Runx1t1 causes the downregulation of Csf-1 (a hematopoietic cytokine known to cause activation of microglia) and Runx3 (a tumour suppressor)." (PMID 22697290, 2012). "Unexpectedly, 9 genes showed the inverse association, including the tumor suppressor genes: RUNX1, CBX7, PRDX2 and PRDX3." (PMID 23077491, 2012). "Haploinsufficiency of RUNX1 leads to the loss of function of this gene (probably a tumor suppressor function)." (PMID 21339820, 2011). "Univariate Cox analysis further highlighted genes whose expression was most strongly associated with patient survival including, POSTN and RUNX1 that were found to be common to the stromal reaction of both tumor types." (PMID 21611158, 2011). "Further investigation is warranted to ascertain whether the inhibition of CEBPA and RUNX1 mutations can activate tumor immunity." (PMID 40313949, 2025). "Aberrations of the RUNX1 gene ascribed by chromosomal translocation and mutations are frequently detected in hematological malignancies, implying that RUNX1 acts as a classic tumor suppressor." (PMID 36831211, 2023). "This transcription factor exhibits seemingly contradictory effects in different cancers, since RUNX1 has been implicated as a tumor suppressor gene in solid tumors (e.g., breast and gastric cancer), while it functions as an oncogene in colorectal, ovarian, head and neck cancers." (PMID 36949071, 2023). "In addition, we observed that patients with promoter 2 loss have RUNX1 expression abolished while patients with exon deletions do not show significant difference in expression compared to unmutated tumours." (PMID 35396535, 2022). "After adjusting for confounders (such as age, stage, sex, race, and tumor purity) in the regression model, we found a significant association between CAFs infiltration and RUNX1 expression in the prognosis of patients with cancer patients, such as BLCA, BRCA-LumB, CESC, LGG, READ, SARC." (PMID 35534796, 2022). "Our findings indicate that RUNX1 expression is increased in various tumors, and thus may be linked to tumor progression and patient prognosis." (PMID 35534796, 2022). "Moreover, RUNX1 expression levels can reflect the infiltration of cancer-associated fibroblasts (CAFs) in tumor tissues." (PMID 35534796, 2022).
tumor (continued). "In addition, RUNX1 was found to downregulate the expression of yes-associated protein (YAP) to deteriorate tumor progression." (PMID 35634311, 2022). "In the present study, RUNX1 showed abnormal methylation in primary NSCLCs, and the reduced expression of RUNX1 was associated with poor overall survival, suggesting that RUNX1 may play a role as a tumor suppressor in normal bronchial epithelial cells." (PMID 32498288, 2020). "Fijneman and colleagues found a set of RUNX1 target genes in mouse colon indicative of changes in gut homeostasis, that is, genes involved in inflammation and intestinal metabolism, which are known to increase the risk of tumor development." (PMID 32812032, 2020). "We conclude from these clinical data that as tumors advance from early stage to a more aggressive phenotype, loss of Runx1 may promote tumor progression." (PMID 28407681, 2017). "However, PCR analysis of tumor-bearing spleens showed that the intact Runx1 allele was strongly retained in the primary tumors, even in pIpC-treated mice." (PMID 27056890, 2016). "RUNX1 has been implicated as a tumor suppressor in several solid tumors including breast cancer, esophageal adenocarcinoma, colon cancer and possibly prostate cancer but acts as an oncogene in head/neck squamous cell carcinomas, endometrial cancer, and epithelial cancer." (PMID 26697518, 2015). "Runx1 is a member of the mammalian Runx family encoding for the transcription factors Runx1, 2 and 3 that may function as tumor suppressors binding to specific DNA sequences namely PEBP2 sites (TGT/CGGT)." (PMID 26030000, 2015). "In addition, we evidence that E2 and G-1 regulate through GPER the expression of miR144 and Runx1 in cancer-associated fibroblasts (CAFs), which are main stimulatory components of the tumor microenvironment." (PMID 26030000, 2015). "This suggests that mutationsin the gene encoding RUNX1, coupled with the loss of a tumor-suppressing protein, maycontribute to the development of cancer in the cells that line the breast ducts." (PMID 25415051, 2014). "Several of the upregulated genes encoded adhesion receptors, secreted proteins and cytoskeletal components, including CDH11, POSTN and MYO5B, along with RUNX1, a master regulator of differentiation processes in different tissues implicated in cell transformation and tumor progression." (PMID 21611158, 2011). "However, mechanisms underlying the implied RUNX1-mediated tumour suppression remain elusive." (PMID 26916619, 2016). "We further analyzed the expression profiles of JMJD1C and RUNX1 across various tumor types using the TCGA database." (PMID 39450904, 2025). "Surprisingly, leukemic blasts were completely depleted 14 days after CD19 CAR-T cell infusion, including CD19-positive tumor cells, and the levels of RUNX1::RUNX1T1 fusion gene decreased from 327.64% to 144.82%." (PMID 40761794, 2025). "RUNX1 is a tumour suppressor and is crucial for the formation of the GI tract’s epithelium and for maintaining the balance of the intestinal stem/progenitor cell population." (PMID 39325241, 2025). "Clinically, activation of the RUNX1/SLAMF3 axis is closely associated with CRLM progression and correlates with a reduced proportion of clinically beneficial C1QC+ tumor‐associated macrophages (TAMs)." (PMID 40448626, 2025). "In T1 samples we detected an overrepresentation of pathways involving signaling by tyrosine kinases, VEGF, RUNX1 and Netrin1, indicating an active interaction between neoplastic cells and tumor microenvironment (TME)." (PMID 40918137, 2025). "Multi-plex IHC confirmed co-localization of RUNX1 with FAP protein at the tumor core and USF2 with PDGFRA expression at the tumor margin." (PMID 39870619, 2025). "RUNX1 is an important regulator of tumour angiogenesis and invasion mediated through the upregulation of key molecules such as matrix metalloproteinases (MMPs) and vascular endothelial growth factor A (VEGFA)." (PMID 41573648, 2025).